TNF (tumor necrosis factor)
Diseases named in the same sentence as TNF in open-access papers (continued):
Sharing a sentence is not in itself a finding about the gene and the disease.
diabetes (continued). "We next aimed to study a possible role for enhanced circulating IL-1β in the observed diabetic endothelial dysfunction, determining its plasmatic levels in the streptozotocin-induced diabetic rats, as well as those of other pro-inflammatory cytokines, like TNF-α." (PMID 25518980, 2014). "Together with data documenting elevated cytokines and free fatty acids in people with type 1 diabetes, the results herein suggest that TNF and FFA may play a role in the etiology of many of the unique pathologies associated with diabetes ranging from autoimmunity to refractory wound healing." (PMID 24466329, 2014). "Importantly, TNFα knockout mice do not develop diabetes even when given a high galactose diet known to cause diabetes in control mice." (PMID 25073020, 2014). "The increase in macrophage-derived TNF-α and IL-1β in the circulation during periodontitis also supports the idea that chronic periodontitis is involved in the pathogenesis of systemic inflammatory diseases, including atherosclerosis, cardiovascular disease, and diabetes." (PMID 24363500, 2013). "Finally, studies have demonstrated the existence of a chronic systemic inflammatory state in diabetes, including endothelial dysfunction, platelet hyperactivity, increased inflammatory markers such as C-reactive protein, interleukin-6 (IL-6), and tumor necrosis factor-α (TNF-α)." (PMID 24386004, 2013). "Additionally, whereas the mean time before development of low blood glucose readings observed in our nine cases was 4.2 months, some instances describe episodes of hypoglycemia occurring within a few hours of TNF inhibitor therapy in patients with pre-existing diabetes." (PMID 22234148, 2012). "In the present study we found that TNFα−/− deficient mice exhibited higher basal levels of VCAM-1 protein in retinal vessels and sVCAM-1 in plasma than wt mice, but these mice failed to up-regulate IL-6 and IL-1β mRNA and VCAM-1 protein in response to diabetes." (PMID 20856927, 2010). "TNF-α (B = 1,7, P = 0,01) and IL-6 (B = 1,51; P = 0,04) levels remains significantly elevated after adjustment for sex, age, left ventricular ejection function, body mass index, coronary heart disease, smoking, hypertension and diabetes mellitus with linear regression analysis." (PMID 19909503, 2009). "In the current study, we investigated the role of the inflammatory cytokine TNF-α in the apoptotic cell death of retinal endothelial cells during early and late stages of diabetic retinopathy using a rat model of streptozotocin-induced diabetes and a mouse model of long-term galactosemia." (PMID 19641635, 2009). "Early in the course of diabetes mellitus (DM), mRNAs for IL-1β, TNF-α and other pro-inflammatory mediators are increased in the retina, partly from activated microglia." (PMID 19088876, 2008). "Therefore, TNF-α is likely to be crucial for the pathogenesis of diabetes in patients with OSAS." (PMID 20066132, 2008). "This supports there being an important role for TNFR2 in determining TNF responses and inflammatory disease pathogenesis, and further genetic and functional experiments will be required to test the importance of TNFR2 variants in controlling islet responses and diabetes susceptibility." (PMID 17254331, 2007). "It was found that nine active ingredients in sweet potato leaves act on 90 targets related to diabetes, with the main targets for their blood glucose-lowering effects being AKT1, GAPDH, STAT3, TNF, and EGFR." (PMID 41515064, 2026). "In diabetes, endothelial cells express higher levels of VCAM‐1 due to stimuli like hyperglycemia, TNF‐α, and AGE accumulation." (PMID 41567175, 2026). "This work aimed to clarify how polymorphisms in the TNF gene relate to metabolic syndrome (MetS), type 2 diabetes mellitus (T2DM), and a broad spectrum of cardiometabolic characteristics, while also determining their impact on circulating TNF‐α concentrations." (PMID 41926520, 2026).
diabetes (continued). "It is also involved in the treatment of metabolic diseases, such as diabetes, inflammation, and cancer, by modulating signaling pathways (NF-κB, PI3K/AKT/mTOR, RAS/RAF) and inflammatory markers (IL-6, IL-1β, TNF-α)." (PMID 42282446, 2026). "Recent studies also showed that SGLT2i had anti-inflammatory effects in patients with type 2 diabetes mellitus, reducing not only CRP levels but also TNF-α and IL-6." (PMID 40134442, 2025). "Investigating other immunological markers such as IL-10, tumor necrosis factor-α, T-regulatory cells, or IgA secretion represents a promising area for future research for better characterization of the immunomodulatory mechanisms by which probiotics could influence glycemic control in diabetes." (PMID 40422866, 2025). "Fangchinoline, another major active component of S. tetrandra, effectively downregulates IL-6 and TNF-α levels by inhibiting p38 MAPK pathway activation, while improving the levels of GLU, Cr, ALB in STZ-induced diabetes rats." (PMID 41031161, 2025). "The relative expression of RAGE, TNF‐α and TGF‐β genes was significantly higher in the diabetes group compared to the healthy group." (PMID 39607899, 2025). "Among these, seven key targets (JUN, AKT1, ESR1, CASP33, TNF, SRC, and IL6) were found to have the highest network connectivity, indicating their central role in treating diabetes with Chaga." (PMID 40508014, 2025). "In the final model with all predictors, VIF’s were the following: age = 1.22, sex = 1.04, hypertension or CVD = 1.18, diabetes = 1.26, cancer = 1.01, IL-6 = 1.27, TNFR1 = 1.99, IL-1b = 1.04, TNF-a = 1.55, IL-10 = 1.11, GDF15 = 2.16." (PMID 41280118, 2025). "Key targets such as JUN, AKT1, ESR1, CASP3, TNF, SRC, and IL6 were identified as central regulators in diabetes-related pathways, with molecular docking confirming strong binding interactions between Chaga-derived phytochemicals and these targets." (PMID 40508014, 2025). "Participants with diabetes had significantly higher hs‐CRP, IL1‐β, TNF, IL‐6 and IFG levels compared to the controls." (PMID 40525652, 2025). "This meta-analysis highlights the significant potential of probiotics in improving inflammatory and oxidative stress markers like CRP, TNF-α, and MDA, while boosting antioxidant defenses such as GSH, TAC, and NO in patients with diabetes mellitus." (PMID 40123937, 2025). "However, TNF-α may be embryotoxic when increased in serum and tissue in diabetes mellitus." (PMID 41295285, 2025). "Manna reported that L‐cysteine supplementation reduced NF‐κB phosphorylation and the secretion of TNF‐α, MCP‐1, IL‐8, IL‐1β, and IP‐10 by increasing AMPK phosphorylation and PPARγ expression against vascular inflammation in diabetes mediated by PI3K." (PMID 41280738, 2025). "GI: gastrointestinal; ERAS: Enhanced Recovery After Surgery; HPA: hypothalamic-pituitary-adrenal; TNF-α: tumor necrosis factor-alpha; T2DM: type 2 diabetes mellitus." (PMID 41589142, 2025). "Elevated serum TNF-α in DKD and T2DM supports its role in driving the transition from diabetes to DKD." (PMID 41318413, 2025). "Pro-inflammatory cytokines, such as tumor necrosis factor-alpha (TNF-α), interleukin-6 (IL-6), and interleukin-1β (IL-1β), are upregulated in individuals with diabetes, contributing to insulin receptor desensitization and impaired glucose uptake." (PMID 40563357, 2025). "According to studies on the effective role of crocin in diabetes and reducing its complications, the goal of this study is to investigate the comparative effect of crocin and Los on RAGE, TGF‐β and TNF‐α gene expression in liver tissue." (PMID 39607899, 2025). "In diabetes with MAFLD, TNFRSF1A activation induces NF-kappa B translocation, resulting in the production of pro-inflammatory factors like IL-6 and TNF-α, which exacerbate liver inflammation." (PMID 40918148, 2025).
diabetes (continued). "Palmitic acid, a saturated fatty acid found in pork and beef, induces TNF-α production through TLR4, contributing to the development of diabetes and atherosclerosis." (PMID 38396804, 2024). "According to our TNF‐α ELISA results, the highest amount of TNF‐α in the serum was determined in the diabetes group." (PMID 39479688, 2024). "In our investigation of IL6 and TNFα, we found that baseline IL6 levels were significantly lower in the cancer group compared to the control group, even when adjusted for BMI, diabetes, and parity." (PMID 38339282, 2024). "Factors such as lipopolysaccharide, oxidized LDL, TNF-α, and IL-1β have been noted for inducing PCSK9 secretion in various organs, contributing to conditions like hyperlipidemia, atherosclerosis, diabetes, and hypertension." (PMID 38762465, 2024). "Although the results of other conducted studies are inconsistent, they indicate that mothers with pre-pregnancy diabetes show abnormal pro–inflammatory protein/cytokine concentrations, such as IL–8, IL–6, CRP, TNF–α and IFN–γ." (PMID 38308265, 2024). "As almond oil displayed anti-diabetes activity in streptozotocin-induced rats, Clostridium_sensu_stricto_1 was positively correlated with FBG, MDA, TNF-α, IL-1β, and Keap1 and was negatively correlated with insulin, body weight, SOD, CAT, Nrf2, and HO-1." (PMID 39403395, 2024). "We observed that after stent implantation co-release of TNFα with IL-1ß or IL8 are the major cytokines that are correlated with various conditions, such as in diabetes and NSTEMI patients with AMI after PCI." (PMID 38216681, 2024). "Intriguingly, the hematopoietic depletion of NOD1 mitigated the diabetes-induced expression of CXCL1 and CXCL2; TNFα and IL10 remained unaffected." (PMID 38336763, 2024). "At the end of treatment, compared with control group, in diabetes, MIRI of diabetes and treatment groups the myocardial TNF-α and IL-6 levels were significantly increased, respectively (P < 0.05)." (PMID 38422326, 2024). "In diabetes context, it has been demonstrated that the ADAM17 inhibitor JTP-96193 reduced TNF-α release from the fat tissue, prevented development of diabetes, and improved insulin resistance in mouse models of obesity and diabetes respectively." (PMID 38576768, 2024). "Prior studies have discovered elevated amounts of inflammatory markers such as IL-1β, TNF-α, and IFN-γ, which were presented in human with diabetes, pig with malnutrition, and mice fed high-carbohydrate diets." (PMID 38668364, 2024). "Increased TNF concentrations alongside IFN-γ and IL-1β concentrations were measured in lung homogenates from mice with chronic streptozotocin-induced diabetes (vs. euglycemic mice) which coincided with greater areas of inflammation in the lung tissue." (PMID 39649174, 2024). "The present study investigated the effects of Andaliman (Z. acanthopodium) fruit extract on biological markers relevant to diabetes management, namely BGL, TNF-α, and TRPA-1." (PMID 39101085, 2024). "A decrease in muscle strength is associated with a rise in inflammatory markers such as tumor necrosis factor-alpha (TNF-alpha), interleukin-6 (IL-6), and c-reactive protein (CRP), which can trigger the incidence of diabetes." (PMID 38276133, 2024). "The results showed that intravitreal injection of AAV-sh-USP25 alleviated diabetes-induced retinal inflammation 8 weeks after STZ injection, as evidenced by reduced expression levels of Iba-1, MCP-1, IL-1β, and TNF-α." (PMID 38436811, 2024). "The cytokine tumor necrosis factor-α (TNF-α), and its receptors, 1 and 2 (TNFR1, TNFR2), are members of TNFR superfamily, and are important mediators of chronic inflammation in diabetes mellitus." (PMID 38893645, 2024). "Many early findings have identified the proinflammatory effect of NF-κB, tumor necrosis factor-α (TNF-α), and interleukin-6 (IL-6) on endothelial dysfunction in diabetes." (PMID 38645427, 2024).
diabetes (continued). "We conducted a comparative analysis of baseline marker levels between the study and control groups, including adiponectin, leptin, IL6, TNFα, IGF1, and IGF2, while also adjusting for BMI, parity, and diabetes." (PMID 38339282, 2024). "In patients with diabetes, carotid PVAT surrounding the atheromatous plaques showed an increase in the mRNA levels of tumour necrosis factor-α (TNF-α), monocyte chemoattractant protein-1 (MCP-1), and interleukin-6 (IL-6)." (PMID 38667739, 2024). "Golimumab, a Tumor Necrosis Factor Alpha (TNF-α) blocker, or placebo was administered in participants within 100 days of diagnosis of stage 3 T1D and who had at least one diabetes-related autoantibody." (PMID 39568817, 2024). "Diabetes-enhanced IL-17 stimulates the expression of other inflammatory mediators such as IL-6, IL-8, PGE2, TNF-α, and RANKL and can indirectly enhance osteoclastogenesis, thereby increasing periodontal tissue damage." (PMID 38614881, 2024). "Increased TNF‐α and ICAM‐1, predicted the incidence of DPN over 5 years in Chinese diabetes patients." (PMID 37795833, 2024). "One study measured elevated HGF levels in the retinas of mice with STZ-induced diabetes and showed that HGF supplementation improved pericyte survival after TNFα stimulation, suggesting potential relevance of HGF in vascular permeability in DR." (PMID 39716241, 2024). "Of the 37 pathways associated with downregulated genes, the most relevant pathways to β-cell biology and/or diabetes included MAPK signaling, apoptosis, TNF signaling, NFKβ signaling, insulin resistance, and pancreatic cancer." (PMID 39022651, 2024). "Diabetes mellitus positively influenced TLR-2 expression on macrophages but adversely affected IL-6 and TNF-α levels." (PMID 39456722, 2024). "TNF-α, a multifaceted proinflammatory cytokine, is recognized for its central role in both the pathogenesis and prognosis of various diseases, including cancer and diabetes mellitus (DM)." (PMID 38406163, 2024). "Consistent with previous studies, our findings demonstrate elevated levels of TNF-α, IL-6, and NF-kB in STZ-induced diabetic rats, reinforcing the link between diabetes and cardiac inflammation." (PMID 39496097, 2024). "Additionally, it has been observed that pancreatic cancer patients with diabetes have high levels of interleukin-1β and tumor necrosis factor (TNF)-α in the tumor microenvironment, which may help to explain the compromised beta-cell function seen in these patients." (PMID 38835644, 2024). "In chronic conditions, gene encoding pro-inflammatory cytokines such as interleukin (IL)-1, IL-2, IL-6, Tumor necrosis factor (TNF)-α, and Monocyte chemoattractant protein (MCP)-1 play crucial roles in diabetes." (PMID 38164478, 2024). "Enrichment analysis revealed that these targets were mainly enriched in the estrogen signaling pathway, TNF signaling pathway, and AGE-RAGE signaling pathway in diabetics, which were mainly related to oxidative stress and hormonal regulation." (PMID 38257113, 2024). "With the mediation of TNF-α, LOX was reportedly downregulated in inflammatory conditions such as diabetes and osteoporosis, thereby suppressing cell growth and reducing the pluripotent cell pool." (PMID 38390397, 2023). "The analysis of individual studies on miR-146 in the context of diabetes yielded a heatmap that showcased the prevalence of several genes, namely IRAK1, TRAF6, IL-6, TNF-α, NUMB, EGFR, and TGFβ-1, among others." (PMID 37560309, 2023). "In this issue, we discussed how the residual aqueous fraction of E. conyzoides has modulatory potential against some of the metabolite derangements seen in diabetes, including elevated levels of oxidative stress marker (MDA), IL-1β and TNF-α." (PMID 37065804, 2023). "The Mitchelstown cohort of the Cork and Kerry Diabetes and Health Diseases Study in Ireland reported that levels of inflammatory biomarkers (i.e., CRP, IL-6 and TNF-α) were lower in individuals with higher HEI-2015 scores." (PMID 37347305, 2023).
diabetes (continued). "Another meta-analysis encompassing 14 RCTs among individuals with diabetes corroborated the favorable effects of aerobic exercise on the levels of the inflammatory biomarkers CRP and TNF-α." (PMID 37986064, 2023). "In the primary study group of children and adolescents with diabetes, we have found significant positive correlations between VEGF and TNF-a, as well as VEGF and the TNFa/IL-35 ratio." (PMID 37893230, 2023). "Among subjects with diabetes, those with TIR ≤ 70% had higher levels of IL-1α, IL-1β, IL-6, IL-12 p70, IL-16, LIF, M-CSF, MCP-1, MCP-3, RANTES, TNF-α, TNF-β, and b-NGF, and lower levels of IL-1α, IL-4, IL-10, GM-CSF, and MIF than individuals with TIR > 70%." (PMID 37893217, 2023). "Empagliflozin substantially decreased renal production of pro-inflammatory cytokines and chemokines (including tumor necrosis factor (TNF)), urine indicators of kidney inflammation (such as IL-6), and apoptosis in a diabetes-induced rat model." (PMID 37047011, 2023). "Imbalance between antioxidants and reactive oxygen species in diabetes usually stimulates the production of ADAM17 and TNF-α." (PMID 37089941, 2023). "Likewise, loss of periostin suppressed diabetes-triggered upregulations of the pro-hypertrophic genes (ANP, BNP, β-MHC), pro-fibrogenic genes (Col I, Col III, α-SMA), pro-inflammtory genes (IL-1β, IL-6, TNF-α) and pro-oxidative genes (NOX2, NOX4, 12-LOX) at the mRNA levels." (PMID 37993768, 2023). "CAD: coronary artery disease; CRP: c-reactive protein; IL6: interleukin 6; MDA: malondialdehyde; T2DM: type 2 diabetes mellitus; TAC: total antioxidant capacity; TNF-α: tumor necrosis factor-alpha." (PMID 38034261, 2023). "Our data demonstrated that the serum proinflammatory cytokines IL-1β, TNF-α, IL-2, IFN-γ, and IL-4 and the anti-inflammatory cytokine IL-10 were dysregulated in diabetes and improved by OI intervention." (PMID 36918798, 2023). "In this study, through bioinformatics analysis, we screened seven DCRGs, including PPARG, MMP9, CTNNB1, TNF, TGFB1, PTGS2, and HIF1A, and established a DCIN to comprehensively understand the diabetes-inflammation-cancer interaction." (PMID 37033970, 2023). "In the studied group of children and adolescents with diabetes, significant positive correlations were found between VEGF and TNF-α (r = 0.52, p < 0.001), TNF-α/IL-35 ratio (r = 0.59, p < 0.001)." (PMID 37893230, 2023). "The endpoints for the first one were CRP, TAC, MDA, NO, and GSH among individuals with T2DM, while the studied outcomes for the other one were TNF-α, CRP, IL-6, and NO among subjects with diabetes." (PMID 36239789, 2023). "Based on the studies conducted in patients with hypertension and diabetes, treatment with spironolactone is accompanied by a decrease in the serum levels of many inflammatory markers such as CRP and TNF‐α." (PMID 37933420, 2023). "The signaling pathway involved in TNF signaling pathway, MAPK signaling pathway, IL-17 signaling pathway, AGE-RAGE signaling pathway in diabetes complications, etc." (PMID 38013385, 2023). "In our study, diabetes elevated the prefrontal cortex and hippocampal gene expression of NfκB, IL-1β, and IL6, as well as the immunoexpression of TNF-α and GFAP, which are considered indicators of astrocyte activation." (PMID 38105928, 2023). "Additional constraints include the fact that there are merely three prospective cohort studies examining the correlation between serum TNF-α levels and DPN in patients with diabetes mellitus." (PMID 38179375, 2023). "JNK is a subfamily of MAPKs and plays a critical role in the regulation of insulin signaling, inflammation, apoptosis, and caspase-3 activity in diabetes and the upregulation of pro-inflammatory cytokines such as MCP-1, IL-6, IL-8, and TNF-α in AD pathology." (PMID 38006400, 2023).